NOD2 (nucleotide binding oligomerization domain containing 2)
Diseases named in the same sentence as NOD2 in open-access papers (continued):
Sharing a sentence is not in itself a finding about the gene and the disease.
infection (continued). "In this section, we summarize the mechanisms of mycobacterial control/killing, which have been examined as a function of NOD2 status: nitric oxide (NO), bacterial burden during in vitro cellular infections, autophagy, and host cell death modality." (PMID 37262021, 2023). "Another study using BCG-infected mice showed that AMs down-regulated NOD2 expression within 2 weeks of infection." (PMID 37262021, 2023). "Targeting the NOD2 pathway in the classical vaccine approach, treating infection and trained-innate immunity, continues to be promising and can be informed by studies on mycobacteria but requires further research before clinical applications can be tested." (PMID 37262021, 2023). "Like our previous study and as shown inFigure 3(b), ELMO1 KO ileum EDMs had lower number of internalized bacteria after 3h of infection, as compared to both WT and NOD2 KO ileum EDMs." (PMID 36694274, 2023). "BMDMs and J774A.1 cells infected with live Mtb up-regulated Nod2 transcripts up to 10.6-fold within 24 hours of infection." (PMID 37262021, 2023). "Nucleotide‐binding oligomerization domain 2 (Nod2) functions to monitor bacterial peptidoglycans entering cells and plays an important role in anti‐infection and immune response control." (PMID 36169246, 2022). "Violin plots demonstrate that Nod1, Nod2 or Ripk2 were expressed by very few ME cells of any category, prior to NTHi infection." (PMID 35903351, 2022). "The activation of the NOD2 signaling pathway is required for the production of type I IFN after infection with three other ssRNA viruses: VSV, IVA, and parainfluenza virus." (PMID 36146565, 2022). "Our trend of decreased lymphocytes in Nod2-KO and DKO mouse lungs at three weeks post-infection with Mtb is similar to results with Nod2-KO mouse lungs at 4 weeks post-infection with BCG Russia." (PMID 35418999, 2022). "Studies showed that the Bacillus Calmette–Guérin (BCG) vaccine against tuberculosis induces NOD2-dependent protection against secondary infections through epigenetic reprogramming of monocytes/ macrophages." (PMID 36613481, 2022). "TRL4 and NOD2 are expressed in odontoblasts layer more abundantly than in other human pulp stroma cells, which can provide significant defense and anti-infection responses of the dental pulp." (PMID 35053286, 2022). "NOD2 is one of the pivotal innate immune sensors, which can recognize pathogen infection and induce subsequent innate immune response." (PMID 36304988, 2022). "The molecules and pathways involved in infection-induced memory are NOD2; possibly viral RNA; and NOD-, LRR-, and pyrin domain-containing protein 3 (NRLP3), which is an intracellular sensor that detects a broad range of microbial molecules." (PMID 36613481, 2022). "The transcripts of Tlr1, Tlr5, Tlr11, and Nod2, Nlrp1a, Naip2, and Nlrc4 were significantly higher in the Nlrp3−/− than wild-type mice on day 7 post-infection." (PMID 34690967, 2021). "Infection of a murine macrophage cell line with M. ovipneumoniae increases levels of nucleotide-binding oligomerization domain-containing 2 (NOD2) and NOD2 along with activation of c-Jun NH2-terminal protein kinase (JNK) induces autophagy." (PMID 34252097, 2021). "For this reason, the essential role of NOD2 in host innate and adaptive immune responses against infections with Mycobacterium spp." (PMID 34777348, 2021). "We found here that NOD2-/- mice had elevated bacterial loads in the early phase of infection, but were unimpaired in pathogen elimination." (PMID 33747981, 2021). "In mid-later stages of infection, however, the attenuated type I IFN signal by the NOD2 deficiency would be sufficiently compensated by the operation of other PRRs such as TLR2 and TLR4." (PMID 34777348, 2021). "The infection of NOD2-/- mice with T. cruzi strain isolated from the digestive patient induced a decrease in intestinal motility." (PMID 32986710, 2020).
infection (continued). "RSV-infected epithelial cells express NOD2 within 2 h after infection and siRNA-mediated knockdown of NOD2 reduced activation of IRF3 and IFN-β production in RSV-infected epithelial cells." (PMID 31952261, 2020). "NOD2 is well recognized as one of the pivotal innate immune sensors, which can sense pathogen infection and induce subsequent innate immune response." (PMID 32144252, 2020). "The histopathological analysis of the colon demonstrated a moderate inflammatory lesion in the sub serous and muscular layer, more pronounced in NOD2-/- animals than C57BL/6 during the acute phase of infection." (PMID 32986710, 2020). "NOD2-/- animals presented more intense focal inflammation in the colon and jejunum wall during acute and chronic phases of infection impacting in the thickness of the muscular layers and ganglionic elements of the enteric nervous system." (PMID 32986710, 2020). "In attempt to evaluate the tissue parasitism, inflammation and hypertrophy of the gastrointestinal tract, histopathological analysis was performed in WT and NOD2-/- in the acute (19 days) and chronic phases (12 months) of infection." (PMID 32986710, 2020). "In fact, we observed that NOD2 deficient mice showed high TLR2 and inflammatory mediators expression during the acute phase of the infection." (PMID 32986710, 2020). "NOD1 is constitutively expressed in intestinal epithelial cells, while NOD2 is upregulated by treatment with specific pro-inflammatory cytokines or by infection with invasive bacteria." (PMID 29616010, 2018). "Efficient immune recognition of Aspergillus is crucial to protect against infection, and previous studies suggested a role for NOD2 in this process." (PMID 29980664, 2018). "A large literature reported that TLR stimulation, required to initiate innate and adaptive immunity upon infection, is modulated by NOD2." (PMID 28253332, 2017). "Similar to RNA viruses, HCMV upregulates NOD2 as early as two hours post-infection and for up to 24 hours afterward." (PMID 28253332, 2017). "Taken together, NOD2 seems to inhibit M. abscessus infection by initiating cytokine production during the early phase of infection." (PMID 29163541, 2017). "Colonic mucin-2 mRNA was, however, down-regulated upon C. jejuni-infection of both Nod2−/− IL-10−/− and IL-10−/− mice, whereas expression levels were lower in infected, but also naive Nod2−/− IL-10−/− mice as compared to respective IL-10−/− controls." (PMID 28752081, 2017). "Mechanistically, Nod2 contributed to the oxidative stress generation (ROS/RNS) for A. baumannii control during early time points of infection." (PMID 29234083, 2017). "NOD2 has been implicated as a cytosolic sensor of M. tuberculosis that drives IFN-α and IFN-β expression upon infection." (PMID 29230217, 2017). "Contradictory results about the role of NOD2 in the induction of pro-inflammatory cytokines by macrophages in response to infection by L. monocytogenes were also reported in vitro." (PMID 28253332, 2017). "In the present study we therefore applied the secondary abiotic murine IL-10−/− infection model to further elucidate the impact of Nod2 in C. jejuni-host interactions." (PMID 28752081, 2017). "The pulmonary bacterial load was significantly higher in Nod2−/− mice compared with wild type controls during the early time point (4 h) post-infection (p = 0.0002)." (PMID 29234083, 2017). "Consistent with the higher bacterial load, A. baumannii-induced neutrophil recruitment, cytokine/chemokine response and lung pathology was also exacerbated in Nod2−/− mice at early time points post-infection." (PMID 29234083, 2017). "Nod2 signaling plays a critical role in controlling intracellular infection with bacteria, including mycobacteria." (PMID 27830463, 2017). "At 15 min after the infection, phosphorylation of p38 and JNK was highly induced only in the WT BMDMs compared with those of NOD2-deficient cells." (PMID 29163541, 2017).
infection (continued). "To further confirm the role of Nod2 in the early innate immune control of A. baumannii in the lungs, we also compared the A. baumannii load between the wild type and Nod2−/− mice at an additional early time point post-infection (12 h)." (PMID 29234083, 2017). "Again, contrary to our data, ER stress contributes to inflammation during an infection with Brucella abortis in a NOD1/NOD2 dependent manner and the unfolded protein response has been shown to strengthen NF-κB dependent inflammation." (PMID 28545453, 2017). "Polyubiquitination of the NOD2-effector RIP2 was significantly diminished upon infection with ESX-1-deficient M. tuberculosis when compared to wild-type bacteria, identifying RIP2 as a major downstream effector of NOD2 in the recognition of M. tuberculosis." (PMID 29230217, 2017). "At day 7 following peroral C. jejuni strain 81–176 infection, Nod2 mRNA was down-regulated in the colon of secondary abiotic IL-10−/− and wildtype mice." (PMID 28752081, 2017). "Effective control of NOD2 signalling is thus critical to reduce excessive inflammation during both infection and other immune-mediated diseases." (PMID 28656966, 2017). "Infection in MDP-pretreated cells induced NOD2 mRNA significantly more than infection only (265- vs 50-fold)." (PMID 26830977, 2016). "In summary, our study presents the unique activities of bacterial MDP on HCMV suppression via NOD2 activation either following infection or in the setting of persistent NOD2 activation." (PMID 26830977, 2016). "To determine the role of NOD2 in leprosy infection, we silenced NOD2 gene expression in human monocytes using short interfering RNAs (siRNAs) and measured the induction of IL-32 mRNA in response to infection with live M. leprae." (PMID 27297389, 2016). "After 6 hours of infection, we observed a significant increase (P < 0.05) in Nod2 relative transcript expression in BMDMs exposed to live tachyzoites." (PMID 27377650, 2016). "Neither pTBK1, pIRF3, nor NF-κB were induced in MDP-treated cells after infection at MOI 1, suggesting that NOD2-downstream signaling cannot overcome higher titer infection." (PMID 26830977, 2016). "Our study demonstrates that NOD2 is crucially involved during the skin stage of infection, as natural infection of NOD2−/− mice with L. sigmodontis leads to a significantly increased worm burden during the early phase of infection." (PMID 28004792, 2016). "Consistent with this idea, overstimulation of NOD2 at the same time as infection with S. Typhimurium leads to a CARD9- and NOD2-dependent decrease in pro-IL-1β expression." (PMID 27670879, 2016). "Using L. sigmodontis, the murine model for human tissue invasive filarial infections, we provide the first evidence that NOD2 is also essential for the early immune response against incoming infectious larvae during infection with filarial nematodes." (PMID 28004792, 2016). "There was no such induction after MDP treatment in infected shNOD2 cells irrespective of MOI, confirming the requirement and specificity of NOD2 for MDP activities during infection." (PMID 26830977, 2016). "We investigated the effect of MDP structure on the innate immune response, finding that infection of monocytes with M. leprae induces IL-32 and DC differentiation in a NOD2-dependent manner." (PMID 27297389, 2016). "To assess the pattern of Nod2 expression during the infection of macrophages, we evaluated the messenger RNA codifying this receptor in mouse bone marrow derived macrophages (BMDMs) during N. caninum infection in vitro." (PMID 27377650, 2016). "As most human pathogenic filariae contain Wolbachia endobacteria that synthesize the MDP-containing cell wall precursor lipid II, NOD2’s role during infection with the rodent filaria Litomosoides sigmodontis was investigated." (PMID 28004792, 2016). "Here, we demonstrate that infection of monocytes with M. leprae induces the NOD2-dependent production of IL-32 as well as DC differentiation." (PMID 27297389, 2016).
infection (continued). "Collectively, these results indicate that Nod2 is recruited to the vacuole during the infection, contributing to the production of pro-inflammatory cytokines and nitric oxide." (PMID 27377650, 2016). "This increased worm burden is due to delayed NOD2-dependent neutrophil recruitment into the skin during the initial phase of the infection." (PMID 28004792, 2016). "The reduced mortality of Nod2−/− mice was also observed after LD100 infection protocols; approximately 40% of these mice survived during the observation period of 30 days." (PMID 27377650, 2016). "Strikingly, we observed that despite decreased pro-inflammatory cytokine production and increased of burden parasite, Nod2−/− mice were highly resistant to lethal infections." (PMID 27377650, 2016). "We found that infection of macrophages induced increased expression of Nod2, which colocalized with the parasites’ vacuoles." (PMID 27377650, 2016). "pneumoniae D39 strain, Nod2-/- and Wt mice had similar bacterial loads in lungs, blood and spleen at 6, 24 and 48 hours after infection." (PMID 26673231, 2015). "While Nod2-/- and Wt mice also had similar bacterial loads after infection with the more virulent S. pneumoniae 6303 strain, Nod2-/- mice displayed a reduced bacterial clearance of the normally avirulent unencapsulated D39Δcps strain." (PMID 26673231, 2015). "To this end we measured cytokines and chemokines in whole lung homogenates obtained from Nod2-/-and Wt mice at several time points after infection." (PMID 26673231, 2015). "Cytokine and chemokine levels in whole lung homogenates were not different between Nod2-/- and Wt mice with the exception of IL-6 concentrations, which were higher in lungs of Nod2-/- mice 24 hours after infection (P<0.05)." (PMID 26673231, 2015). "We found elevated IL-6 levels in lung homogenates taken from Nod2-/- mice at 24 and 48 hours post-infection (P<0.05 and P<0.01)." (PMID 26673231, 2015). "The aim of our study was to evaluate the impact of 13 different SNPs, including in NOD2 and TLR 4, on transplant-associated complications such as infection, need for dialysis and the outcomes of the recipients." (PMID 24393249, 2014). "In summary, the results suggest that NOD2 expression in DSCs plays an important role in protecting the embryo and preventing infection in the maternal-fetal interface." (PMID 24932916, 2014). "Shaw and colleagues further reported that WT infected mice survived the infection, whereas NOD2-/- had all died until day 21 p.i., but data regarding intestinal histopathology were lacking." (PMID 25141224, 2014). "Until day 7 post infection (d7 p.i.), NOD2-/- animals had lost significantly more body weight as compared to WT mice (15.3±1.5% vs 12.4±4.1%; p<0.05), indicative of a more compromised clinical condition of the former." (PMID 25141224, 2014). "Cell-free supernatants were collected from infected HFFs-NOD2 and infected HFFs-control cells 4 days post infection (dpi) and were used for a second cycle infection of fresh HFFs at equivalent volumes." (PMID 24671169, 2014). "We report that infection with human cytomegalovirus (HCMV) results in significant induction of NOD2 expression, beginning as early as 2 hours post infection and increasing steadily 24 hours post infection and afterwards." (PMID 24671169, 2014). "After infection, real-time PCR was performed to determine the presence of mRNAs encoding NOD1 and NOD2." (PMID 25443778, 2014). "We demonstrate that S. Typhimurium ΔmsbB infection triggered exacerbated inflammation in Nod1−/−, Nod2−/− and DKO mice compared to C57BL/6 mice." (PMID 25423082, 2014). "It was demonstrated that the band density of NOD1 continuously increased after prolonged infection by P. aeruginosa, while other autophagy proteins (e.g. NOD2, Beclin1 or Atg5) had the same band density even after prolonged infection." (PMID 25433669, 2014).
infection (continued). "The expression of NOD2 mRNA and protein were markedly elevated following infection with the gram-positive pathogen S. pneumoniae." (PMID 25443778, 2014). "Enhanced resistance of Nod2-/- mice to lethal infection correlated with a reduction in the frequency of CD8+ T cells." (PMID 23526993, 2013). "At the early stages of infection, NOD2 signaling was shown to activate the CCL2/CCR2 axis that resulted in the recruitment of inflammatory monocytes to the site of infection, which initiated IL-12-mediated bacterial clearance." (PMID 24381573, 2013). "Our data show for the first time that lethal infection is associated with the upregulation of surface and intracellular PRRs, including TLR2, Nod1, and Nod2." (PMID 23526993, 2013). "The same group further demonstrated that NOD1 and NOD2 were crucial for the induction of mucosal Th17 responses during the early stages of infection with Citrobacter rodentium and S. enterica Typhimurium." (PMID 23162548, 2012). "Here, we demonstrated that macrophages from NOD1-, NOD2-, and Rip2-deficient mice produced lower levels of TNF-α following infection with live Brucella abortus compared to wild-type mice." (PMID 22203860, 2012). "Taken together, this study demonstrates that NOD1, NOD2 and Rip2 are dispensable for the control of B. abortus during in vivo infection." (PMID 22203860, 2012). "We propose a model where Nod2 has an enhancing role in activating inflammation in early infection, but moderates inflammation after prolonged exposure to the organism through induction of tolerance." (PMID 21387014, 2011). "It is possible that molecules such as Nod2 can play roles in both resistance and tolerance during the course of infection." (PMID 21387014, 2011). "Because Nod2 is involved in the gut immune response, we tested if the infection route influences the animal survival by infecting Nod2−/− mice in the C57BL/6j background with 5×104 CFU of the YPIII(pIB102) strain via the intra-peritoneal route." (PMID 18648508, 2008). "This phenomenon is referred to as ‘trained immunity’, in which innate immune cells are reprogrammed, leading to an enhanced response to subsequent infection, mediated by various signaling pathways, including those involving nucleotide-binding oligomerization domain-containing protein 2 (NOD2)." (PMID 40732729, 2025). "This suggests that previous SARS-CoV-2 infection may alter NOD2 responsiveness to subsequent microbial stimuli, potentially shaping the immune system’s ability to respond to new infections." (PMID 40732729, 2025). "Similarly, in mrigal, the expression levels of NOD1 and NOD2 in the gills, liver, kidney, and intestine significantly increased after infection with either S.agalactiae or Aeromonas hydrophila." (PMID 40218399, 2025). "Screening for recipient susceptibility genes such as TLR4, NOD2, and DEFB, in combination with donor infection-related indicators like CMV serostatus, enables the classification of recipients into low-, intermediate-, or high-risk categories for infection." (PMID 41550938, 2025). "Mice lacking Nod2 (Nucleotide-binding oligomerization domain-containing protein 2), Myd88 (Myeloid differentiation primary response protein), and Tlr2 (Toll-like receptor 2) are more susceptible to infection with S. aureus than mice expressing these genes." (PMID 39178306, 2024). "Our results showed a positive modulation of the NOD1, NOD2, and NLRP3 genes after 24 h of co-culture, suggesting that in the early stages of infection, the transcription of these genes may be associated with the transcription of the TLR genes." (PMID 38248981, 2024). "According to previous reports, during infection with several RNA viruses, NOD2 is activated and leads to the activation of a protective innate immune response mediated by interactions with adaptors including RIP2, MAVS, OAS2, CARD9, etc., resulting in activities against the pathogens." (PMID 38668261, 2024).